MPO (myeloperoxidase)
Diseases named in the same sentence as MPO in open-access papers (continued):
Sharing a sentence is not in itself a finding about the gene and the disease.
colitis (continued). "Our studies also showed that AS-IV attenuated the DAI and MPO activity, downregulate the expression of Tnf-α and Il-1β and increase the level of Il-10 and Tgf-β in a dose-dependently manner in DSS-induced colitis mice." (PMID 34589089, 2021). "The DSS-induced colitis mice treated with control liposomes presented several colitis symptoms, evidenced by increased DAI scores, shorter colon length, increased MPO activity, serious pathological damage in colons, and tiliroside alleviated these symptoms." (PMID 33868286, 2021). "Based on our results, Lcn2 and MPO were suitable as biomarkers to differentiate between the 2% and 3% DSS groups, whereas Hgb was sensitive to distinguishing colitis conditions at concentrations below 2% DSS." (PMID 33673349, 2021). "Mice given 4.5 mg/kg bodyweight of zearalenone for 1 week expressed IL-1β, IL-18, and MPO mRNA transcripts and NLRP3 protein in colonic tissue and exhibited colitis-like symptoms." (PMID 33927703, 2021). "The effect of ZS40 on oxidative stress in the serum of colitis was evaluated by monitoring antioxidant indicators and lipid peroxidation biomarkers, such as T-SOD, CAT, MPO, and MDA." (PMID 34867317, 2021). "As expected, we observed that after treatment with EphB2-EVs, the MPO activity and MDA expression were significantly decreased in DSS-induced colitis, while the activity of SOD and GSH level were remarkably increased." (PMID 33722292, 2021). "The elevation in the colonic contents of MPO, MMP-9, and MCP-1 was intensified in mice exposed to acrylamide as compared with the control colitis mice." (PMID 33995942, 2021). "Previously, reduced tissue MPO and plasma pro-inflammatory markers (TNF-α, IL-6) were also demonstrated in response to KYNA and SZR-72 treatments in experimental colitis." (PMID 34475875, 2021). "In colitis induced by the TNBS model, EA decreased MPO activity, IL-1β concentration, iNOS expression, and MDA concentration but increased IL-10 concentration in intestine tissues." (PMID 35095910, 2021). "Antibiotic treatment suppressed the mitigating effects of ALS on the symptoms of colitis, including the shortened colonic length, increased DAI scores, colon damage, and elevated activities of MPO." (PMID 34836184, 2021). "7-day long administration of 2.5% DSS to HFD-fed mice resulted in a distinct colitis phenotype at week 16th confirmed by an increase of DAI, IL-6 mRNA expression and MPO activity." (PMID 34380504, 2021). "The specific affinity between NPs and MPO was explored in the imaging of colonic tissue sections, after being collected from the used DSS-induced colitis mice model, demonstrating that HSA NPs and MPO were co-localized in the colonic tissue." (PMID 34443866, 2021). "These include reductions in colitis symptoms, pro-inflammatory markers TNF-α, IL-1β, IL-6, MPO, and PGE2, and levels of NO and MDA, whereas TGF-β expression, GSH levels, and enzyme activities of SOD, CAT, GPx, and GR, were increased." (PMID 34073220, 2021). "Exposure to IS significantly induced colon shortening, myeloperoxidase activity, IL-1β, IL-6, and TNF-α expression, and NF-κB+/CD11c+ cell population in the colon, resulting in colitis." (PMID 33731795, 2021). "Previous studies have shown that TQ treatment mitigated colonic inflammation with a reduction in colonic myeloperoxidase activity, malondialdehyde, and increased glutathione levels in dextran sulfate sodium (DSS)-induced colitis in mice." (PMID 33920708, 2021). "In intrarectal administration of TNBS-induced colonic inflammation model, EA at ST36 decreased TNF-α, IL-6, and IL-1β levels in plasma and MPO activities in colonic tissues." (PMID 35095910, 2021). "In particular, results from previous study showed that apo-bLF was more efficient than the holo form in decreasing MPO, IL-1β, and TNF-α synthesis in trinitrobenzenesulfonic acid (TNBS)-induced colitis in rats and dextran sulfate (DSS)-induced colitis in mice." (PMID 34901112, 2021).
colitis (continued). "Taurine supplementation significantly attenuated the weight decrease, diarrhea severity, colon shortening, and the increase in the colonic MPO activity in dextran sulfate sodium (DSS)-treated mice, another animal colitis model, mimicking clinical IBD." (PMID 33803551, 2021). "Pretreatment of rats with telmisartan reduced TNBS-induced colitis decreased the disease severity and suppressed the inflammatory response by attenuating the function of TNF-α, prostaglandin E2, and Myeloperoxidase and restoring IL-10." (PMID 33628160, 2021). "In contrast, apoA-I transgenic mice had less severe symptoms and MPO activity in both the DSS and TNBS colitis models." (PMID 33922158, 2021). "To evaluate the infiltration of immune cells in the colon, we performed MPO and F4/80 staining to detect neutrophils and macrophages, respectively, in colonic tissue sections from mice with DSS-induced colitis." (PMID 34059646, 2021). "Similarly, a study in acetic acid-induced and DSS-induced colitis showed that oral treatment with low-MW chitosan with a DD of 85–90% at a dose of 20 mg/kg for 5 and 7 days, respectively, led to a significant reduction in MPO activity and a marked improvement in clinical colitis symptoms." (PMID 33138176, 2020). "Anthocyanins inhibited MPO activity, and the increase of pro-inflammatory cytokines in mice with TNBS-induced colitis." (PMID 32722619, 2020). "After colitis, the levels of SOD and GSH were reduced in colon tissue, while those of MDA and MPO were elevated." (PMID 32849906, 2020). "In the current study, we found that alpinetin decreased the activation of NF-κB, the expression of pro-inflammatory mediator genes, the activity of MPO, and the production of TNF-α and IL-6 in DSS colitis mice." (PMID 32372959, 2020). "The level of MPO and ALP concentrations confirmed that chitosan has its own anti-inflammatory effect in experimental colitis, which is roughly comparable to the effect observed with 5-ASA." (PMID 33138176, 2020). "Intraperitoneal administration of the minor tobacco alkaloid and nicotinic receptor agonist anabaseine was shown to reduce tissue damage, myeloperoxidase activity, and colonic TNFα expression in a TNBS mouse model of colitis." (PMID 32855621, 2020). "Accordingly, colitis was aggravated by the transfer of γδT17 cells, evidenced by higher DAI, shorter colon length, higher MPO activity, and worse pathological lesion in the colon tissues." (PMID 32929062, 2020). "Muscadine grapes or wine phytochemicals are capable to decrease MPO activity as well as colonic levels of IL-1β, IL-6, and TNF-α in experimental DSS-colitis." (PMID 32429359, 2020). "Our findings showed that MPO and MDA levels in the colon tissue significantly increased, while antioxidant levels markedly decreased in DSS-induced colitis group compared to control group." (PMID 31999939, 2020). "In a rat model of colitis induced by dextran sodium sulphate (DSS), blueberry powder reduced myeloperoxidase (MPO) activity and MDA concentration, but had an insignificant effect on MCP-1 level." (PMID 32722619, 2020). "Pre-treatment of rats with RES lowered MPO activity, and IL-1β, PGE2 and prostaglandin D2 (PGD2) levels from TNBS-induced colitis." (PMID 32722619, 2020). "Treatment of dextran sodium sulfate (DSS)-induced colitis in mice with TQ suppresses malondialdehyde (MDA) levels and myeloperoxidase (MPO) activity with concomitant increase in glutathione levels indicating improvement in colitis-associated tissue damage." (PMID 32486445, 2020). "The VSL#3 treatment determines anti-inflammatory effects in experimental colitis, as evidenced by reduced disease activity index (DAI) score, histological activity index (HAI) score and myeloperoxidase (MPO) activity." (PMID 32429359, 2020). "Several studies have shown that treatment with SOD or high-SOD-producing Lactobacillus significantly reduces colonic myeloperoxidase level, oxidative stress, and inflammation in DSS-induced colitis mice." (PMID 32630643, 2020).
colitis (continued). "Further research has shown that thalidomide can reduce the levels of TNF-α, IL-1, IL-6, MPO, and NO in TNBS-induced mouse colitis, in turn reducing the inflammatory response in CD." (PMID 32766176, 2020). "Embelin also ameliorates DSS-induced colitis in mice by attenuating DAI (Disease Activity Index) scores and tissue MPO accumulation." (PMID 32486445, 2020). "These natural compounds significantly reduced the values of specific serum oxidative and proinflammatory markers (superoxide dismutase, myeloperoxidase, malondialdehyde, prostaglandin E2, TNF-α, IL-β, and C-reactive protein) in TNBS -induced colitis." (PMID 32867139, 2020). "In a dextran-sulfate-induced colitis animal model, Yue and colleagues showed that the polysaccharides ameliorated the inflammatory response through lowering TNF-α, IL-1β, IL-6, and MPO activity and increased AMPK activity." (PMID 32560291, 2020). "Chrysin is also capable of diminishing inflammatory markers such as MPO activity, TNF-α levels and NF-κB activation and translocation to the nucleus if administered previously to DSS-induced colitis mice." (PMID 32377161, 2020). "Intrarectal treatment of colitis with 30 mg/kg chitosan alone and with 30 mg/kg 5-ASA for 3 days led to a significant decrease in MPO, ALP, TNF-α, IL-6, IL-1β and NF-κB in colitis mice compared to untreated mice." (PMID 33138176, 2020). "In DSS-induced experimental mouse model of colitis, CAPE is effective in suppressing pro-inflammatory cytokines and MPO activity, which improves epithelial barrier function." (PMID 32486445, 2020). "CEE suppressed myeloperoxidase (MPO) activity and macrophage marker F4/80 mRNA expression in colonic tissue of mice with DSS-induced colitis, indicating neutrophil infiltration and macrophage accumulation, respectively." (PMID 32059355, 2020). "Aronia consumption inhibits myeloperoxidase (MPO) during T cell transfer, an indicator that neutrophil infiltration is suppressed during colitis." (PMID 31212794, 2019). "Increased MPO and higher iNOS activity were demonstrated after TNBS-induced colitis and they have been related to the chronicity of the inflammation status." (PMID 31731626, 2019). "When the colitis mice were treated with MRS, their activities of SOD and GSH were improved and the levels of MDA and MPO were reduced." (PMID 31182999, 2019). "Treatment of UC with SP, honey, and combination regimen significantly reduced TNF-α, IL-1β, IL-6, MDA, MPO, NO, and PGE2, and increased TAC, GSH, GPx, and SOD in interventional groups compared to the AA-colitis group (P<0.05)." (PMID 34466462, 2019). "Since severity of colitis is evaluated by the DAI, MPO, and the length of colorectum, the effects of Portulaca extract on these parameters were examined." (PMID 29483924, 2018). "Local treatment with P28GST after induction of colitis with TNBS at dose 5 and 50μg/kg of P28GST significantly reduced the levels of colonic MPO induced by TNBS in mice." (PMID 30592734, 2018). "We found that alpinetin (30 mg/kg) showed well reduction of DAI scores, MPO activity, shortening of colon length, histological changes and levels of TNF-α as well as IL-1β in colons of colitis mice, which was restored by CH223191 (10 mg/kg)." (PMID 30166541, 2018). "The findings of this study will provide an insight into the anti-inflammatory efficacy of CAPE during colitis in terms of changes in the levels of the disease activity index (DAI) score, colon MPO, pro-inflammatory cytokines, and epithelial barrier function." (PMID 28528363, 2018). "In a model of trinitrobenzenesulfonic acid (TNBS)-induced colitis in rats, daily gavage of LTF attenuated TNBS-induced colitis as assessed by macroscopic and histologic scoring and myeloperoxidase activity." (PMID 29163511, 2017). "Here, we found that MPO activity, an indicator of neutrophil infiltration, was significantly higher in rats with DSS-induced colitis than in controls; these increases were attenuated by swimming." (PMID 28030847, 2017).
colitis (continued). "TNBS-induced colitis mimics human IBD with respect to several histological alterations, including the mucosal invasion of polymorphonuclear cells (as indicated by MPO activity) and contributions to colon injury." (PMID 28556814, 2017). "Evaluation of the MPO activity is crucial to understand the effects of the HA biopolymer and/or 5-ASA on SD rats with colitis." (PMID 28556814, 2017). "Others have shown that NAC attenuated macroscopic colonic damage and histopathologic changes, decreased colonic MPO activity and ROS, upregulated paraoxonase 1 (an antioxidant enzyme), and scavenged oxygen-derived free radicals in a mouse DSS colitis model." (PMID 28832517, 2017). "Our data showed that intra-rectal administration of madecassic acid (25 mg/kg) effectively ameliorated colitis in mice, as confirmed by reducing DAI scores, protecting against colon shortening, decreasing MPO activity and attenuating pathological lesions." (PMID 28358365, 2017). "MPO activity and MDA levels are elevated, and contents of GSH, superoxide dismutase (SOD) and CAT are significantly reduced in acetic acid-induced colitis." (PMID 28832517, 2017). "In agreement with the macroscopic results previously referred, ARF treatment significantly reduced, and more efficiently than 5-ASA, MPO activity and its expression stimulated by TNBS-induced colitis." (PMID 28329021, 2017). "In the present study, bergenin showed well alleviation of colitis induced by DSS in mice, evidenced by reduced DAI scores, shortening of colon length, MPO activity and pathologic abnormalities in colons." (PMID 29375382, 2017). "In DSS-induced colitis, Westernized HFD-feeding enhanced neutrophil infiltration as indicated by enhanced myeloperoxidase activity, and pea seed albumin extracts reduced inflammatory cell infiltration into the colon." (PMID 28524086, 2017). "Given the relation with NF-κB inhibitors and inflammation, we assessed anti-inflammatory efficacy of API by determining the colon length, myeloperoxidase and DAI score in each group of DSS-induced colitis animals." (PMID 27685808, 2016). "Oral administration of recombinant L. lactis expressing pIGF-I3 attenuated DSS-induced colitis and protected intestinal function by improving CDS, MPO and DAO activities, and inhibiting the increase of colonic occludin level." (PMID 26932768, 2016). "Administration of ghrelin after induction of colitis led to faster regeneration of the colonic wall and reduction in colonic levels of IL-1β, TNF-α, and myeloperoxidase." (PMID 27598133, 2016). "Curcumin treatments were associated with amelioration of macroscopic and microscopic colitis sores, decreased MPO activity, and decreased MDA levels in acetic acid-induced colitis rats." (PMID 26007179, 2015). "Tissue MPO activity was significantly increased in rats with colitis (TNBS) compared to controls (P < 0.001), and the HBO treatment (TNBS/HBO) significantly decreased the MPO activity (P < 0.001)." (PMID 25926972, 2015). "Effect of selected Lactobacillus sp. on myeloperoxidase (MPO) activity, disease activity index (DAI) and colon length, on DSS-induced colitis." (PMID 26645292, 2015). "Myeloperoxidase (MPO) is an enzyme secreted by neutrophils at the site of inflammation and is widely used as a marker of murine colitis." (PMID 26000979, 2015). "Colitis model in mice was determined by disease activity index (DAI), macroscopic tissue damage, histopathological score and myeloperoxidase (MPO) activity." (PMID 25853847, 2015). "In rats with 2,4,6-trinitrobenzenesulfonic acid (TNBS)-induced colitis, melatonin has been shown to decrease caspase-3 activity, malondialdehyde (MDA) levels, myeloperoxidase activity and NF-κB epxression, and to increase glutathione levels." (PMID 25625560, 2015). "In dextran sodium sulphate (DSS) induced colitis in mice, Embelin reduced the mRNA expression of TNF-α, IL-1, IL-6, and colonic MPO." (PMID 26347311, 2015).
colitis (continued). "In accordance with our data, it was earlier shown that the retinoic acid, which has an immunomodulatory effect, ameliorates the TBNS colitis via inhibition of TNF-α, IL-6, IL-1β secretion and MPO activity in mice." (PMID 25853847, 2015). "Compared to water-treated GF mice, which remained completely healthy, the clinical colitis score (CCS) and myeloperoxidase (MPO) were significantly higher in water-treated parental and first filial generation (F1) of mice colonized with biopsy a (aHMA)." (PMID 26697117, 2015). "Diet-induced obesity delays the healing of experimental colitis via decrease in CBF and the increase in MPO activity and the expression and release of proinflammatory mediators." (PMID 25684862, 2015). "The MPO activity and MDA content were up-regulated in colonic homogenate (all P < 0.01), indicating the successfully established rat colitis model." (PMID 24787389, 2014). "In the model of colitis induced by TNBS, polysaccharides of C. montagnei showed reduced levels of IL-6 and NO, as well as others important markers, such as myeloperoxidase." (PMID 24518681, 2014). "In mild colitis mice groups, after 20 mg/kg CK and 100 mg/kg BBR treatment, MPO activity in the colon was reduced by 401±41.29 mU/g (p<0.01) and 235±76.37 mU/g (p<0.05) compared to the model group." (PMID 24504372, 2014). "A bioflavonoid derived from the seeds of Garcinia kola, kolaviron, exhibits an anticolitis effect by reducing nitric oxide, myeloperoxidase activity, TNF-α, and IL-1β in DSS-induced colitis mice." (PMID 25045208, 2014). "Neutrophilic infiltration correlates with tissue MPO activity, which represents the severity of DSS-induced colitis." (PMID 25120575, 2014). "In another study in Sprague-Dawley rats with colitis induced by DNBS, ChE inhibitors neostigmine and physostigmine reduced macroscopic damage and MPO activity in the colon." (PMID 23469045, 2013). "In the present study, HFD induced colon shortening and increased the expression of proinflammatory cytokines and MPO activity in the colon, suggesting that HFD induced colitis." (PMID 23091640, 2012). "Severity of colitis was evaluated by disease activity index (DAI), body weight (BW) change, colon length, histology, myeloperoxidase (MPO) activity, and proinflammatory cytokine production including tumor necrosis factor-α (TNF-α) and interferon-γ (IFN-γ)." (PMID 22647055, 2012). "In the DSS-colitis model, treatment with TLR7 ligands reduced MPO activity in the colon, indicating that the treatment resulted in reduction of neutrophil recruitment." (PMID 22619481, 2012). "MPO activity levels were low in the colonic tissues of normal control mice and markedly increased in mice with DSS-induced colitis." (PMID 23125487, 2012). "Acute and chronic colitis induced by DSS has been used to study changes in metabolically labeled and tissue mucin content and/or changes in epithelial permeability, MPO and pro-inflammatory cytokines." (PMID 21949848, 2011). "The therapeutic efficacy of IG on experimental colitis was assessed by body weight change, colon length, disease activity index (DAI), histological analysis and MPO activity." (PMID 21931839, 2011). "The severity of colonic inflammation in developed disease was evaluated by measuring main parameters CMDI and DAI scores and MPO activity." (PMID 20927245, 2010). "IL-4, IL-10 and INF-y concentrations (ρg/mL), MPO activity (U/mg) in the colon and DNA damage levels (tail moment/100 cells isolated from colon) of DSS-induced colitis rats fed Control, Fish or Soybean/Fish diet." (PMID 20615224, 2010). "In vivo experiments showed that punicic acid and pomegranate seed oil intake decreased neutrophil-activation and ROS/MPO-mediated tissue damage as measured by F2-isoprostane release and protected rats from TNBS-induced colon inflammation." (PMID 19649246, 2009).